FAM66B (family with sequence similarity 66 member B)
Gene: Long non-coding RNA gene on chromosome 8 (7,263,163 to 7,355,364, reverse strand). Ensembl gene ENSG00000215374.
Diseases named in the same sentence as FAM66B in open-access papers:
FAM66B is named in the same sentence as 6 diseases in open-access papers, as found by Europe PMC text mining. Sharing a sentence is not in itself a finding about the gene and the disease. The quoted sentences say what the papers report.
astrocytoma (1 paper, 2023). "Distinctively dysregulated lncRNAs in gliomas include LOC150622 and LINC00645 in glioblastoma, LOC100216479 in diffuse H3K27M glioma, FLJ41350 and FTX in medulloblastoma, TPTEP1 and LOC100144595 in astrocytoma, and LOC100216545, FAM66B, and LOC100499405 in oligodendroglioma." (PMID 37693314, 2023).
esophageal squamous cell carcinoma (1 paper, 2024). Esophageal squamous cell carcinoma (ESCC) is a type of esophageal carcinoma (EC) that can affect any part of the esophagus, but is usually located in the upper or middle third. "FAM66B gene changes have been reported to be involved in esophageal squamous cell carcinoma." (PMID 38792557, 2024).
FAM66B also shares sentences with these, for which no sentence is quoted: glioblastoma (1 paper); glioma (1); medulloblastoma (1); oligodendroglioma (1).